GRPR (gastrin releasing peptide receptor)
Diseases named in the same sentence as GRPR in open-access papers (continued):
Sharing a sentence is not in itself a finding about the gene and the disease.
glioma (12 papers, 2012 to 2025). A benign or malignant brain and spinal cord tumor that arises from glial cells (astrocytes, oligodendrocytes, ependymal cells). "GRPR expression is notably higher on the cell membranes of glioma cells compared to healthy brain cells." (PMID 39911305, 2025). "Clinical trials have demonstrated high sensitivity and specificity in identifying different grades of gliomas, thus establishing GRPR as a valuable target for image-guided surgery." (PMID 40005958, 2025). "NeoB is a theranostic vector for GRPR-overexpressing gliomas, among other malignancies, marked as the first-in-human trial of this specific radioligand." (PMID 40806525, 2025). "In vivo studies demonstrate that GRPR antagonists (RC-3095) inhibited the growth of the C-6 glioma by 60%, and when combined with temozolomide, a further reduction in tumor size occurred." (PMID 34539578, 2021). "In studies with experimental gliomas, the treatment with GRPR antagonists increased the survival time by inhibiting the growth of xenografts of human glioblastomas cell lines (U-87G,U-373MG) in nude mice." (PMID 34539578, 2021). "Gastrin-releasing peptide receptor antagonists inhibit the growth of human U-87MG and U-373MG gliomas xenografted into nude mice." (PMID 23251133, 2012). "We have recently shown that the stimulatory effect of GRPR activation on proliferation of glioma cells depends on PI3K signaling and is potentiated by co-activation of the cAMP/PKA pathway." (PMID 23251133, 2012). "Therefore, we developed a novel PET/NIR dual-modality image probe targeting gastrin-releasing peptide receptor (GRPR) in glioma cells to enhance tumor visualization and improve the accuracy of sampling." (PMID 38169486, 2024). "However, in another study, the proliferation of the rat glioma C-6 cell line was stimulated by Bn (which can activate both GRPR and NMBR), and this effect was inhibited by the GRPR antagonist RC-3095." (PMID 34539578, 2021). "GRPR activation by GRP or bombesin stimulates the growth of glioma cell lines." (PMID 23251133, 2012). "In an immunocytochemical study of 34 cases of human gliomas [WHO grade 1 astrocytomas (three cases), grade 2 (four cases), grade 3 (three cases), and grade 4-glioblastoma multiforme (24 cases)], GRPR was detected in 100%." (PMID 34539578, 2021). "Gastrin‐releasing peptide receptor (GRPR), also known as bombesin (BBN) receptor subtype II, is overexpressed in multiple tumor types, including glioma." (PMID 33532584, 2021). "One study investigated the mRNA expression levels of each of the human BnRs (GRPR, NMBR, BRS-3) in recurrent gliomas in nine patients." (PMID 34539578, 2021). "Experimental findings demonstrate that Bom/PEG-PCL-Tat micelles exhibit a high uptake rate by GRPR-positive C6 glioma cells while showing no significant increase in uptake by GRPR-negative COS7 cells." (PMID 39911305, 2025). "In one study, the expression level of GRPR in gliomas (content, intensity, or area ratio) was not related to tumor grade, and the GRPR content index did not correlate with patient survival." (PMID 34539578, 2021). "All gliomas had uptake and correlated with tumor density of GRPR, not NMBR/BRS-3." (PMID 34539578, 2021).
gastrointestinal stromal tumor (10 papers, 2012 to 2025). "[68Ga]Ga-NeoBOMB1 has shown promising PET imaging of GRPR expression in gastrointestinal stromal tumors in Phase I/IIa clinical studies." (PMID 40775579, 2025). "One prominent example is the gastrin-releasing peptide receptor (GRPr), which is predominantly expressed mainly in human tumors such as prostate, breast and gastrointestinal stromal tumors and small-cell lung cancer." (PMID 37285007, 2023). "Since overexpression of the GRPR has been reported in various cancer types, e.g. prostate cancer, breast cancer, gastrointestinal stromal tumors (GISTs) and other tumors." (PMID 34228236, 2021). "For example, gastrin releasing peptide receptor (GRPr) has been shown to be overexpressed in prostate, breast, small cell lung cancer and gastrointestinal stromal tumors." (PMID 23024746, 2012). "The gastrin-releasing peptide receptor (GRPR) has been identified as a promising target for cancer imaging and therapy as it is overexpressed in various solid tumors, e.g., prostate, breast, and gastrointestinal stromal tumors (GIST)." (PMID 37640941, 2024). "GRPR is also highly expressed in gastrointestinal stromal tumor (GIST) patients (~80%), so that NeoB could be a valuable potential drug candidate to treat such tumors that lack effective therapies when resistance to receptor tyrosine kinase (RTK) inhibitors occurs." (PMID 33801382, 2021).
breast tumors (9 papers, 2018 to 2026). "For instance, in the T47D cell line in vivo, the radiotracer [99mTc]Tc‐DB 15 (N4‐AMA‐DGA‐[DPhe6‐Sar11‐Leu13‐NHEt] BBN) demonstrated excellent metabolic stability and enhanced GRPR‐specific uptake in breast tumours." (PMID 41555955, 2026). "The results of this study showed that GRPR-targeted radiotracers can act as an alternative in PET/CT imaging of ER+ breast tumors." (PMID 38279185, 2024). "The Gastrin-Releasing Peptide Receptor (GRPR) is over-expressed in estrogen receptor (ER) positive breast tumors and related metastatic lymph nodes offering the opportunity of imaging and therapy of luminal tumors." (PMID 30645633, 2019). "Findings from this in vitro study suggest that GRPR targeting can be an alternative to 18F-FDG imaging in ER+ breast tumors." (PMID 30645633, 2019). "With respect to breast tumours, 70% of Luminal A and B subtypes exhibit high GRPR expression." (PMID 41555955, 2026). "Notably, in cases where GRPR was overexpressed in breast tumors, 94.6% of metastatic lymph nodes also exhibited high levels of GRPR expression." (PMID 38279185, 2024). "Both the results confirm the GRPR-specific mice breast tumor formation by MDA-MB-231 cells." (PMID 30887136, 2019). "Visualization of GRPR-expressing breast tumors might help to select the optimal treatment." (PMID 40871022, 2025). "GRPR expression and CDH1 expression in breast tumours are inversely correlated." (PMID 40500450, 2025). "We observed elevated GRPR and ESR1 mRNA levels in breast tumours expressing mutated, non-functional ECAD." (PMID 40500450, 2025). "Several findings supported GRPR’s dependence on ERα: the increased GRPR levels in ERα-positive compared with ERα-negative breast tumours; the strong correlation between GRPR mRNA and ERα activation score; and ERα binding to active regions associated with the GRPR promoter." (PMID 40500450, 2025).
metastatic disease (9 papers, 2016 to 2025). "The presented data indicates that nuclear based imaging and therapy has the potential to improve BC patient care in primary as well as in metastatic disease, by targeting GRPR and SSTR2." (PMID 28107508, 2017). "While GRPR expression is substantial in primary PCa (up to 100%) and lymph node metastases (>85%), PSMA expression increases with the transition towards androgen independence, and is most associated with high-grade, metastatic disease." (PMID 31540122, 2019). "Furthermore, we recently reported that BC metastases from GRPR-positive primary BCs also express GRPR, indicating that this imaging method can be applied in both primary and metastatic disease." (PMID 28134770, 2017). "Moreover, because GRPR antagonists can also be labeled with lutetium-177 this opens new avenues for targeted radionuclide therapy in the subset of patients with progressive metastatic disease following conventional treatments." (PMID 30645633, 2019). "PET imaging that targets GRPR is helpful for the diagnosis of early PCa, whereas PSMA is a more appropriate biomarker for high GS disease and metastatic disease and is related to patient prognosis." (PMID 38880858, 2024). "Targeting the GRPR and SSTR2 for nuclear imaging and/or treatment has the potential to improve BC care in primary as well as metastatic disease." (PMID 28107508, 2017). "The use of PET/CT with gastrin-releasing peptide receptor (GRPR) ligand [68Ga]Ga-AMTG has recently been shown to diagnose metastatic disease not detected by 18F-PSMA PET/CT in patients with metastatic castration-resistant prostate cancer." (PMID 40306971, 2025). "Furthermore, they quantitatively analyzed the mRNA levels of GRPR and SSTR2 in 60 pairs of primary tumors and corresponding metastatic tumors using reverse transcription polymerase chain reaction (RT-PCR)." (PMID 38279185, 2024).
pancreatic cancer (9 papers, 2020 to 2025). "On the other hand, bombesin (BBN) derivatives have the ability to recognize the gastrin-releasing peptide receptor (GRPR) that is overexpressed in several human tumors such as breast, prostate, and pancreatic cancer." (PMID 39065597, 2024). "It is known that changes in GRPR expression are observed in pancreatitis and pancreatic cancer; thus, a further promising area of [99mTc]Tc-DB8 imaging applications may be the assessment of pancreatic transplant viability." (PMID 41155959, 2025). "Consequently, [68Ga]Ga-TacsBOMB5 should be more sensitive for detecting GRPR-expressing pancreatic cancer and other cancer lesions adjacent to the pancreas." (PMID 35744904, 2022). "The binding region of this peptide shows agonistic affinity to the gastrin-releasing peptide receptor (GRPR), abundantly expressed in many neoplastic conditions, such as breast, prostate, or pancreatic cancer." (PMID 34452201, 2021). "For instance, HT29 colorectal adenocarcinoma cells, which express high levels of GRPR, exhibited increased sensitivity to SP-G inhibitors, whereas PANC-1 pancreatic carcinoma cells, characterised by low GRPR expression, demonstrated minimal responsiveness both in vitro and in vivo." (PMID 41226822, 2025).
small cell lung carcinoma (9 papers, 2012 to 2025). Small cell lung cancer (SCLC) is a highly aggressive malignant neoplasm, accounting for 10-15% of lung cancer cases, characterized byrapid growth, and early metastasis. "Among several receptors upregulated in cancer cells, the gastrin-releasing peptide receptor (GRP-R) has recently emerged as a promising target for cancer imaging, diagnosing and treatment due to its overexpression on cancerous tissues such as breast, prostate, pancreatic and small-cell lung cancer." (PMID 36834815, 2023).
glioblastoma (7 papers, 2021 to 2025). The most malignant astrocytic tumor (WHO grade IV). "Previously, IRDye800 was used to label a 14-mer peptide targeting the gastrin-releasing peptide receptor (GRPR), which was safely utilized in image-guided surgeries of glioblastoma multiforme in n = 29 patients." (PMID 39199591, 2024). "In an experimental study using intracranial administration of the mouse glioblastoma cell line, CT-2A to make CNS tumors, the administration of the small molecule 77427, which is a GRPR antagonist, inhibited angiogenesis, and smaller tumors developed." (PMID 34539578, 2021). "Moreover, [68Ga]-IRDye800CW-BBN, a near-infrared fluorescence (NIRF) targeting GRPR in glioblastoma multiforme, had also entered clinical trials for further assessments." (PMID 38585455, 2024). "In the human glioblastoma cell lines U138-MG, U-87, and U-373, which have high levels of GRPR receptors and are responsive to GRPR activation, GRPRs’ presence has been detected by both GRPR mRNA expression and immunohistochemical studies." (PMID 34539578, 2021). "In the human glioblastoma cell line U-373MG, Bn peptides (GRP, NMB) stimulate DNA synthesis, which is mediated by GRPR." (PMID 34539578, 2021). "The GRPR antagonists RC-3095, RC-3049-III, RC-3049-Et inhibited the proliferation of the human glioblastoma cell lines U-87-MG, U-373-MG, and U-118MG and in U-118MG; the tumoral expression of VEGF; the expression of PKC-alpha; and the Bcl-2:Bax ratio, indicating a net apoptotic gain." (PMID 34539578, 2021). "In studies on various human glioblastoma cell lines, evidence was provided that the activation of phospholipase C by Bn-related peptides, as well as MAP kinase activation, was due to the activation of GRPRs (GRPR selective antagonism) with GRP more potent than NMB." (PMID 34539578, 2021).
cervical cancer (6 papers, 2015 to 2025). A primary or metastatic malignant neoplasm involving the cervix. "Tumor response to 212Pb-DOTAM-GRPR1 strongly associates with GRPR overexpression, and therefore, it seems reasonable to assess uterine cervix cancer GRPR immunoreactivity for greater insight into the feasibility of using 212Pb-DOTAM-GRPR1 as a radiopharmaceutical treatment." (PMID 36761980, 2023). "GRPR mRNA levels were evaluated in cervical cancer-derived cell lines and in primary keratinocytes expressing HPV16 oncogenes by RT-PCR." (PMID 40242010, 2025). "We first analyzed GRPR mRNA levels in cervical cancer-derived cell lines and in keratinocytes expressing HPV16 E6 and/or E7." (PMID 40242010, 2025). "A greater GRPR mRNA expression was observed in cervical cancer derived cell lines compared to normal cells, although this difference was only evidenced in the HPV-negative C33 cell line." (PMID 40242010, 2025). "Previous studies have shown that variable subsets of uterine cervix cancer cases expressed GRPR ranging from 77% to 88% as evaluated by diverse methods." (PMID 36761980, 2023). "It remains desirable to screen uterine cervix cancer patients by GRPR protein expression level as an enrichment approach for clinical trials evaluating the 212Pb-DOTAM-GRPR1 radiopharmaceutical." (PMID 36761980, 2023). "In this translational oncology study, we tested GRPR protein expression as a potential biomarker to triage uterine cervix cancer patients to a 212Pb-DOTAM-GRPR1 radiopharmaceutical treatment." (PMID 36761980, 2023). "Because GRPR occurs and stimulates cell proliferation in uterine cervix cancer, radiopharmaceutical peptide–receptor cohesion might have a therapeutic value by bringing a cell-killing radionuclide directly to cancer cells." (PMID 36761980, 2023). "The 212Pb-DOTAM-GRPR1 radiopharmaceutical is an α-particle-emitting radionuclide 212Pb, a metal chelator DOTAM, and a GRPR-targeted antagonist that is currently being studied in the metastatic uterine cervix cancer setting (NCT05283330) as well as in a variety of other cancer types." (PMID 36761980, 2023). "Conversely, only half of the metastatic uterine cervix cancer tumors express GRPR at the same level of immunoreactivity; however, such a finding remains exploratory as there were only six metastatic sites sampled and none with a paired primary tumor in our study." (PMID 36761980, 2023). "Characterization of GRPR expression patterns in specific histological subtypes of uterine cervix cancer may help in defining patient population(s) who benefit from 212Pb-DOTAM-GRPR1 as a radiopharmaceutical treatment." (PMID 36761980, 2023). "In summary, our study suggests that the clinical usefulness of GRPR-targeted radiopharmaceuticals in the maintenance or metastatic treatment of uterine cervix cancer might be beneficial based on the high frequency of GRPR overexpression." (PMID 36761980, 2023). "Currently, it is unknown whether GRPR expression in uterine cervix cancer stays relatively stable during tumorigenesis." (PMID 36761980, 2023). "We examined a series of 33 uterine cervix cancer paraffin-embedded tumors in order to establish whether this tumor type overexpresses GRPR at an IRS score of 6 or higher, as 212Pb-DOTAM-GRPR1 is currently being evaluated in clinical trials against tumors showing such a level of expression." (PMID 36761980, 2023). "GRPR mRNA levels in normal keratinocytes, keratinocytes transduced with HPV16 oncogenes E6 and/or E7, and cervical cancer-derived cell lines (C33, SiHa and HeLa) were analyzed using real-time PCR." (PMID 40242010, 2025). "Our results evidenced widespread GRPR expression in cervical cancer and low expression in non-malignant samples." (PMID 40242010, 2025).
cervical cancer (continued). "GRPR mRNA levels were not significantly increased in HPV-positive cervical cancer-derived cell lines compared to normal keratinocytes." (PMID 40242010, 2025). "Prior reports on patient uterine cervix cancer tumors using nonstandard methods for GRPR expression demonstrated that up to 88% of cancer cases express GRPR and that overall GRPR expression prevails in endocervical neoplasia." (PMID 36761980, 2023).
colon cancer (5 papers, 2022 to 2025). "Moreover, GRPR is overexpressed in a variety of malignancies, including breast, prostate, lung, and colon cancers, and the activation of GRPR leads to the proliferation of cancer cells." (PMID 38794191, 2024). "The gastrin-releasing peptide receptor (GRPR) is considered an attractive target for molecular imaging, as it is overexpressed in several high-incidence solid tumors, such as prostate, breast, lung and colon cancer." (PMID 37046825, 2023).
head and neck squamous cell carcinoma (5 papers, 2012 to 2025). A squamous cell carcinoma that arises from any of the following anatomic sites: lip and oral cavity, nasal cavity, paranasal sinuses, pharynx, larynx, and salivary glands. "Few studies were conducted to investigate the GRPR targeting potential in human head and neck squamous cell carcinoma OSCC." (PMID 32651409, 2020). "Furthermore, the gastrin-releasing peptide receptor (GRPR), which is overexpressed in various tumors including head and neck squamous cell carcinoma, provides an ideal target for precision therapy." (PMID 41155020, 2025). "However, few studies had investigated the GRPR targeting potential in human head and neck squamous cell carcinoma." (PMID 35992794, 2022). "Recently, Lango MN13 found that GRPR is overexpressed in both head and neck squamous cell carcinoma (HNSCC) tumors and adjacent normal mucosa from HNSCC patients compared with levels in control mucosa from individuals without cancer." (PMID 32651409, 2020).
neuroendocrine tumors (5 papers, 2013 to 2025). "There are no trials at this time that target the gastrin-releasing peptide receptor (GRP-R) or the integrin αVβ3 or αVβ5 receptors, which have also been identified as potential targets for neuroendocrine tumors." (PMID 39380959, 2023). "After the radiolabeled somatostatin peptide analogues have being used successfully in neuroendocrine tumors for nuclear imaging and therapy, GRPR radioprotections (GRPR radiolagind) have been synthesized and used in preclinical and clinical studies, currently including the prostate." (PMID 33854977, 2021).